RET (ret proto-oncogene)
Diseases named in the same sentence as RET in open-access papers (continued):
Sharing a sentence is not in itself a finding about the gene and the disease.
multiple endocrine neoplasia type 2A (84 papers, 2002 to 2026). "MEN2A, also known as Sipple syndrome, is primarily caused by germline mutations in the RET gene in nearly all cases." (PMID 40934230, 2025). "chose not to include among their primary diagnostic cases a known pathogenic variant in the RET gene associated with multiple endocrine neoplasia type IIA, instead reporting it as a secondary finding." (PMID 39960876, 2025). "Germline mutations in RET are responsible for multiple endocrine neoplasia type 2A (MEN2A), in which PHPT presents alongside medullary thyroid carcinoma and pheochromocytoma." (PMID 41210508, 2025). "Some authors proposed that the clinical characteristics of the MEN 2A syndrome are modified by specific polymorphic variants or haplotypes of the RET gene." (PMID 33938650, 2021). "MEN1 and RET are associated with multiple endocrine neoplasia type I and multiple endocrine neoplasia type II, respectively." (PMID 26530882, 2015). "RET mutations can also be responsible for MEN 2A syndrome (MTC, PC and hyperparathyroidism) or familial MTC (FMTC)." (PMID 22429913, 2012). "In contrast, the same variant in a 25-year-old with MTC and a history of pheochromocytoma may strongly suggest a germline RET variant associated with multiple endocrine neoplasia type 2A (MEN2A)." (PMID 40759574, 2025). "Multiple endocrine neoplasia type 2A (MEN2A) is an inherited disorder related to germline mutations in the RET proto-oncogene (chromosome 10q11)." (PMID 36382757, 2022). "Interestingly, a case of multiple endocrine neoplasia type 2A (MEN2A) with concurrent RNF213 and RET mutations demonstrated potential synergistic effects between genetic predisposition and catecholamine hypersecretion in intracranial stenosis development." (PMID 40508049, 2025). "In addition to the classical cysteine mutations, which were originally shown to be associated with the multiple endocrine neoplasia type 2A (MEN2A) and the M918T mutation that is causative of MEN2B, over the years additional RET mutations have been discovered mainly in FMTC." (PMID 31510104, 2019). "Inherited RET activating mutations are associated with MTC, either alone (familial medullary thyroid cancer [FMTC]) or as part of the multiple endocrine neoplasia type 2A (MEN 2A) or MEN 2B syndromes." (PMID 37627175, 2023). "It is not clear if the association with papillary thyroid microcarcinomas in multiple endocrine neoplasia type 2A (MEN2A) patients is related to specific germline changes of the RET gene or is reflective of how carefully the thyroids of MEN2A patients are examined." (PMID 33495912, 2021). "Multiple endocrine neoplasia type 2A (MEN 2A) was assigned to chromosome 10 by linkage analysis in 1987, when the location of the RET gene was still unknown." (PMID 24281099, 2010).
thyroid tumor (81 papers, 1993 to 2025). A benign or malignant neoplasm affecting the thyroid gland. "Diverse studies have shown that RET/PTC rearrangements are more common in radiation-associated thyroid tumors, and experimental evidence suggests that exposure to ionizing radiation can induce RET/PTC rearrangements in human thyroid cells 24,25." (PMID 39744583, 2025). "Then, we quantified the loss of exon 24 in Dicer1 mRNA in RET/PTC3 Dicer1(−/−) and RET/PTC3 Dicer1(+/−) thyroid tumors compared to RET/PTC3 Dicer1(+/+) mice tumors." (PMID 41002430, 2025). "We show that selpercatinib significantly increased Δψm, and its combination with MitoQ synergistically suppressed RET-mutated human thyroid tumor cells, which we validated using RET-targeted genetic approaches." (PMID 38378752, 2024). "Rearrangements involving receptor tyrosine kinases, primarily RET, are present in a subset of thyroid tumors that lack mutations in either BRAF or RAS." (PMID 39596225, 2024). "If RET mutation occurs elsewhere other than a high-risk site like codon 918, the thyroid tumor tends to present as a PTC with good biological behavior." (PMID 39235852, 2024). "Molecular profiling of tumors often provides diagnostic information like RB1 mutations in retinoblastoma and RET in thyroid tumors." (PMID 37483495, 2023). "Such a strategy in all PHPT patients or in PHPT patients with synchronous thyroid tumors found by ultrasonography would likely prove more cost effective than systematically carrying out RET mutation analysis." (PMID 32375120, 2020). "Medullary thyroid carcinoma (MTC) is a thyroid tumor which can occur as hereditary (20% of cases), due to an activating germline mutation of the REarranged during Transfection (RET) protooncogene, or sporadic (80%), with a somatic RET mutation." (PMID 29774010, 2018). "CCDC6 was originally identified in chimeric genes as caused by chromosomal translocation involving the RET protooncogene in some thyroid tumors." (PMID 23145146, 2012). "In thyroid tumors alteration of RET pathway have been found not only on mutation/overexpression of RET gene, but have been attributed to downstream protein." (PMID 23133451, 2012). "Among the genes that have been shown to differentiate histological subtypes of thyroid tumors and/or to be associated with the expression of thyroid oncogenes (RET/PTC isoforms or BRAFV600E), 78 genes overlapped with the present signature." (PMID 21853153, 2011). "In fact, we have shown the presence of a sequence variant (GGT→AGT: gly→ser), in codon 691 of exon 11 of the RET gene, giving rise to a polymorphism, in 55% of radiation-associated thyroid tumours." (PMID 12085189, 2002). "The blood samples were collected from 12 of our patients with radiation-induced thyroid tumours, and the DNAs extracted from the lymphocytes were screened for the G691S RET sequence variant." (PMID 12085189, 2002). "We previously showed that the multi-kinase inhibitors vandetanib and cabozantinib increase the mitochondrial membrane potential (Δψm) in RET-mutated thyroid tumor cells and that this effect can be exploited to increase mitochondrial enrichment of Δψm-sensitive agents in the tumor cells." (PMID 38378752, 2024). "Therefore, most patients with RET 634 mutations will have adrenal and parathyroid tumors in addition to thyroid tumors." (PMID 35627249, 2022). "Different molecular mechanisms for mixed thyroid tumors have been suggested, like the possible association with the uncommon polymorphism G691S of the RET protooncogene, but the origins of this rare tumor entity remains unclear." (PMID 24711931, 2014). "Moreover, oncogenically mutated forms of REarranged during Transfection (RET) receptor tyrosine kinase are also often detected in certain thyroid tumors and are supposed to drive the pathways." (PMID 24662939, 2014).
thyroid tumor (continued). "Moreover, the C-cell hyperplasia was observed in peritumoural tissue of only two of the 29 sporadic thyroid tumours studied and just one of them presented a serine residue (allele A2) on the codon 691 of the RET protein." (PMID 12085189, 2002). "In this study, we hypothesized that the RET-selective inhibitor, selpercatinib, can increase Δψm and, subsequently, tumor cell uptake of the mitochondria-targeted ubiquinone (MitoQ) to the level to break the mitochondrial homeostasis and induce lethal responses in RET-mutated thyroid tumor cells." (PMID 38378752, 2024). "At this time point, the amount of TUNEL-positive cells was significantly increased in RET/PTC3 Dicer1(−/−) thyroid tumors." (PMID 41002430, 2025). "RT-qPCR analysis revealed an upregulation of Bim in RET/PTC3 Dicer1(+/+) thyroid tumors compared to the WT thyroids from 2-month-old mice." (PMID 41002430, 2025). "In contrast, thyroid tumors from RET/PTC3 Dicer1(+/+) mice showed higher growth and continued to increase in size over time as expected." (PMID 41002430, 2025). "Immunostainings showed comparable Tg, Tg-I and T4 staining intensity and distribution in WT thyroids and RET/PTC3 thyroid tumors." (PMID 41002430, 2025). "The fifth edition of the WHO Classification of Thyroid Tumors incorporates key genetic alterations (i.e., BRAF V600E, RAS mutations, RET/PTC rearrangements, and PAX8–PPARG fusions) into the diagnostic framework for follicular-derived neoplasms." (PMID 41228318, 2025). "A significant increase in the number of vimentin-positive cells was observed in thyroid tumors from 2-, 4- and 8-month-old RET/PTC3 Dicer1(+/+) mice compared to WT thyroids, which was expected given the tumoral context." (PMID 41002430, 2025). "On the other hand, our RET/PTC3 Dicer1(−/−) thyroid tumors showed markedly decreased expression of Dicer1 exon 24 mRNA levels." (PMID 41002430, 2025). "The RET/PTC rearrangement in thyroid tumours was found to be more prevalent in children and young adults." (PMID 38873786, 2024). "This study identified areas where pathologists need additional continuing professional development opportunities to enhance their competencies and better support delivery of care to patients with RET-altered lung or thyroid tumours." (PMID 37277734, 2023). "BRAF positive thyroid tumors have shown sensitivity to RAF and/or MEK inhibitors and RET variants correlate with aggressive phenotype and worse outcome." (PMID 37483495, 2023). "The aim of this study was to identify RET fusion-positive thyroid tumors, correlate them with clinicopathological features, compare them with other mutated carcinomas, and evaluate long-term follow-up of patients." (PMID 37882481, 2023). "Genomic abnormalities related to radiation carcinogenesis, such as RET/PTC translocation, have been observed in genomic analyses of thyroid tumors associated with radiation exposure in humans." (PMID 37824459, 2023). "By comparing gene expression in transgenic RET and BRAF(V600E) thyroid tumors, we identified a zebrafish RET gene signature (n = 178 genes)." (PMID 35510953, 2022). "The ARROW study also showed that pralsetinib was active in other types of RET-positive solid tumors, including other thyroid tumors, cholangiocarcinoma, pancreatic and neuroendocrine tumors." (PMID 36358717, 2022). "The high prevalence of RET/PTC in post-Chernobyl thyroid tumors (87%) highlighted a strong relation between RET rearrangements and radiation exposure." (PMID 33572167, 2021). "RET/PTC1-transgenic (RET/PTC1TG) mice develop slowly progressive thyroid tumors displaying the cytohistological aspects of human PTC." (PMID 29584698, 2018).
thyroid tumor (continued). "Cahill and colleagues have shown that human derived BRAFT1799A- and RET/PTC-bearing thyroid tumor cells, KAT10 and TPC-1 respectively, express lower levels of 14q32-encoded miRNAs miR-323-3p, miR-370-5p, miR-127-3p, miR-299 and miR-154." (PMID 28030816, 2017). "The most prevalent genetic alterations in thyroid tumors are BRAFT1799A mutation and RET/PTC chromosomal rearrangements, which have been extensively explored as prognostic markers and therapeutic targets." (PMID 28030816, 2017). "To mimic thyroid tumors expressing BRAFV600E or RET/PTC3 oncogenes, we examined PCCl3 cells with inducible expression of BRAFV600E or RET/PTC3." (PMID 26397139, 2015). "The reported RET /PTC prevalence in thyroid tumors varies greatly in different series and this difference can be attributed to ethnical and geographic variations as well as to the different sensitivities of detection methods and tumor heterogeneity." (PMID 24868250, 2013). "CCDC6 has been also reported to be rearranged with genes different from RET in thyroid and non-thyroid tumours." (PMID 23145146, 2012). "We have previously reported that thyroid tumor cell lines expressing RET oncoproteins after RPI-1 treatment maintained strong activation of focal adhesion kinase (FAK), one of the most prominent phosphorylated proteins in the PTC cell line TPC-1." (PMID 20955590, 2010). "RPI-1 showed high effectiveness in controlling the growth of thyroid tumors by inhibiting tyrosine kinase activity, expression, and signaling of RET in TT cell line." (PMID 20955590, 2010). "PTC is strongly associated with prior irradiation to the head and neck, likely resulting in chromosome breakage and rearrangement with fusion of the RET tyrosine kinase domain to various breakpoint sites, clearly demonstrated in post-Chernobyl thyroid tumors." (PMID 19830129, 2009). "RET-PTC 3 transgenic mice give rise to thyroid tumours with a more solid phenotype than those seen in RET PTC1 transgenic mice, and in vitro RET-PTC3-transfected cells show a higher growth rate than RET-PTC 1-transfected cells." (PMID 15150580, 2004). "A high prevalence of chromosomal rearrangements involving the RET gene was found among these radiation-induced thyroid tumors." (PMID 12805663, 2001). "Indeed, Dicer1 mRNA levels were downregulated in thyroids from 4- and 8-month-old RET/PTC3 Dicer1(+/+) thyroid tumors compared to WT thyroids." (PMID 41002430, 2025). "We analyzed by RT-qPCR their mRNA expression in RET/PTC3 thyroid tumors and WT thyroids." (PMID 41002430, 2025). "First, we aimed to determine whether RET/PTC3 thyroid tumors exhibit downregulation of Dicer1 mRNA expression compared to WT thyroids, as observed in human PTC." (PMID 41002430, 2025). "The observed reduced weight of the RET/PTC3 Dicer1(−/−) thyroid tumors could result from increased cell death, potentially through apoptosis." (PMID 41002430, 2025). "Notably, pralsetinib and selpercatinib have demonstrated unprecedented efficacy in the treatment of patients with lung or thyroid tumors, driven by RET gene rearrangements." (PMID 40405293, 2025). "However, Dicer1 exon 24 mRNA levels were markedly decreased in thyroid tumors from 2, 4- and 8-month-old RET/PTC3 Dicer1(−/−) tumors." (PMID 41002430, 2025). "These mutations are RET/PTC and THADA/IGF2BP3 translocations, which have been hypothesized as oncogenic events in thyroid neoplasms." (PMID 37444504, 2023). "Larotrectinib (NTRK inhibitor) and selpercatinib (RET inhibitor) have shown dramatic efficacy in clinical trials in both solid tumors and hematologic malignancies, including a limited number of thyroid tumors harboring NTRK and RET fusions included in these studies." (PMID 35015563, 2022).
thyroid tumor (continued). "The results have shown a significant increase in the percentage of Ki-67 positive cells (p < 0.01; Tukey’s multiple comparisons test) in thyroid tumors from either RET/PTC1TG;Patz1+/− or RET/PTC1TG;Patz1−/− mice, compared to those from RET/PTC1TG;Patz1+/+ mice." (PMID 29584698, 2018). "In addition, the incidence of RET/PTC rearrangement was shown to be increased in thyroid tumors that developed after radiation exposure." (PMID 26886957, 2016). "However, it has been shown that thyroid tumor cells, characterized by a constitutive activation of the MAPK pathway (due to the mutations of oncogenes such as RAS, BRAF, and RET/PTC), are more susceptible to NK cell-mediated killing." (PMID 27563819, 2016). "Importantly, we show that activated DNA-PKcs is elevated in medullary thyroid tumor samples and that expression correlates with expression of RET in thyroid tumors." (PMID 26065416, 2015). "On the other hand, thyroid tumor cells may actively participate in leukocyte recruitment, as RET oncogenic activation induces upregulation of the pro-inflammatory interleukins IL1α and IL8 in vitro." (PMID 26536459, 2015). "In a series of 96 thyroid tumours whose mutational profiles of BRAF, IDH1 and NRAS mutations and RET/PTC were previously determined, we investigated MLH1 and MGMT expression and methylation status by qPCR and methylation-specific PCR after bisulphite treatment, respectively." (PMID 23414134, 2013). "Tissue samples from 13 post-Chernobyl childhood thyroid tumours that occurred within a short period of time (4–8 years) after the Chernobyl accident have been investigated by interphase FISH analysis for rearrangements of RET." (PMID 16641909, 2006). "However, in RET/PTC3 Dicer1(−/−) thyroid tumors, Bim mRNA expression remained slighly upregulated." (PMID 41002430, 2025). "However, we found that thyroid tumors from 4-month-old and 8-month-old RET/PTC3 Dicer1(−/−) mice were significantly smaller than those from RET/PTC3 Dicer1(+/−) and RET/PTC3 Dicer1(+/+) mice, indicating that the complete loss of Dicer1 leads to a reduction in tumor size." (PMID 41002430, 2025). "Indeed, we observed increased γH2AX staining in RET/PTC3 Dicer1(−/−) thyroid tumors, which corresponded with the elevated TUNEL staining, supporting the hypothesis that cell death is triggered by the accumulation of DNA damage." (PMID 41002430, 2025). "Interestingly, RET/PTC1TG mice heterozygous for the Patz1-knockout mutation do not significantly differ from RET/PTC1TG;Patz1+/+ control mice as far as thyroid tumor incidence is concerned, but their thyroid cancer phenotype is significantly more aggressive than that of controls." (PMID 29584698, 2018). "Importantly, RET can induce the overexpression of c-MET in this type of thyroid tumor." (PMID 23509459, 2013). "On the other hand, the WT allele (478 bp) was present in the follicular cells from WT thyroids and RET/PTC3 Dicer1(+/−) and RET/PTC3 Dicer1(+/+) thyroid tumors, as expected, but also in RET/PTC3 Dicer1(−/−) thyroid tumors." (PMID 41002430, 2025). "Activated proto-oncogenes, such as RET/PTC, RAS, and BRAF, in thyroid tumors can trigger mitogen-activated protein kinase (MAPK) cascades, thereby promoting the spontaneous transformation of cells into a proinflammatory phenotype." (PMID 40490818, 2025). "Tyrosine kinase inhibitors that target RET, such as vandetanib and cabozantinib, have showed promise in clinical studies, while particular inhibitors for RET/PTC-positive thyroid tumors are currently being investigated." (PMID 38501105, 2024). "This study investigated the impact of two gene fusions, RET/PTC and THADA/IGF2BP3, that have been described as oncogenic events in thyroid neoplasms." (PMID 37444504, 2023). "Afirma XA detected many fusions seen in thyroid neoplasms like PAX8::PPARG, ETV6::NTRK3, CCDC6::RET, NCOA4::RET, STRN::ALK, AGK::BRAF, SND1::BRAF and RBPMS::NTRK3." (PMID 37510219, 2023).